LGALS3 (galectin 3)
Diseases named in the same sentence as LGALS3 in open-access papers (continued):
Sharing a sentence is not in itself a finding about the gene and the disease.
cardiovascular diseases (continued). "Additionally, many new biomarkers have been discovered with increasing utility in cardiovascular disease, including soluble suppression of tumorigenicity 2, galectin 3, and biomarkers of fibrosis, metabolism, and inflammation." (PMID 33977287, 2021). "Also, additional studies with larger sample sizes are required to investigate the interaction between genetic variant, gene expression, and circulating Galectin-3 in T2DM and cardiovascular diseases." (PMID 34616230, 2021). "Galectin-3 has recently been proposed as a novel biomarker for cardiovascular disease in adults." (PMID 29327139, 2018). "Finally, an ancillary observation is that a large body of literature indicates a role of galectin-3 as a prognostic marker in cardiovascular disease." (PMID 29160796, 2017). "Overall, these findings underscore the value of galectin-3 as a biomarker for assessing diastolic dysfunction across different patient populations, providing insights into its pathophysiological role and clinical implications in cardiovascular disease management." (PMID 39063659, 2024). "Hence, urinary galectin-3 levels may serve as a prognostic biomarker for fatal outcome in patients with cardiovascular diseases." (PMID 37189804, 2023). "However, The source of increasing cardiac Galectin-3 in various cardiovascular diseases remains unclear." (PMID 26582585, 2015). "Previous studies have shown that increased circulating galectin-3 is associated with the severity of cardiac dysfunction and ventricular remodeling in patients with myocardial infarction, acute or chronic HF, or even in general population without overt cardiovascular disease." (PMID 32893848, 2020). "Galectin-3 levels are higher in T2DM patients, with or without cardiovascular disease, and our results also show increased galectin-3 values in these patients." (PMID 32294902, 2020). "Newer ones such as galectin-3, lysophosphatidylcholine, copeptin, sST2, S100B, myeloperoxidase and GDF-15 have been extensively studied in recent years as alternatives with an increased sensitivity for cardiovascular diseases, but also with significant results in the field of neurology." (PMID 34821692, 2021).
kidney disease (51 papers, 2011 to 2025). "In renal disease, elevated serum galectin-3 concentrations are associated with the onset of CKD, development of renal fibrosis, and rapid renal function decline." (PMID 40564142, 2025). "A prospective study showed that patients with higher amounts of urinary galectin-3 (≥510.8 pg/mL) compared to those with lower galectin-3 levels (≤354.6 pg/mL) had a 4.6-fold higher risk of kidney disease progression." (PMID 37189804, 2023). "There was growing evidence of high galectin-3 associated with elevated risk of renal deterioration and galectin-3 seemed to have a potential role in treatment of kidney disease." (PMID 31080833, 2019). "Recent studies reveal the potential of galectin-3 as a biomarker for kidney disease progression and its implications in cardiovascular morbidity and mortality among CKD patients." (PMID 40564142, 2025). "Galectin-3 (Gal-3): Gal-3 is a beta-galactoside binding lectin that relates to kidney disease progression and also participates in various pathways such as inflammation, fibrosis, and myocardial remodeling." (PMID 41517298, 2025). "In regard to their potential to identify disease and its progression, patients with kidney diseases have higher levels of urinary adiponectin, lipocalin-2, leptin, galectin-3 and IL-6." (PMID 37189804, 2023). "Among them, galectin-3 has been extensively studied for its involvement in kidney diseases." (PMID 39769262, 2024). "In addition, galectin-3 is involved in many other disease conditions including heart disease, kidney disease, viral infections, and autoimmune and neurodegenerative disorders." (PMID 36914828, 2023). "Given its involvement in inflammatory and fibrotic processes, the determination of urinary galectin-3 levels may become a non-invasive biomarker for advanced kidney diseases." (PMID 37189804, 2023). "The current review aims to present a general survey on galectin-3 expression in nephrogenesis, kidney injury in animal models, clinical renal diseases, and renal transplantation, as well as its potential role in the treatment of kidney disease." (PMID 27089335, 2016). "Previous studies have suggested that increased galectin-3 may be an important biomarker for renal disease." (PMID 27089335, 2016). "This review discusses a general survey on galectin-3 expressions in nephrogenesis, kidney injury animal models, clinical renal diseases, renal transplantation and the potential role of galectin-3 for treatment in kidney disease." (PMID 27089335, 2016). "Tff3, Vgfa, Vgfb, Vgfc, Il1b and Lgals3 were not differentially expressed in the present study even though they have been implicated in kidney disease." (PMID 26673451, 2015). "Plasma galectin-3 (Gal-3) is associated with organ fibrosis, but whether urinary Gal-3 is a potential biomarker of kidney disease progression has never been explored." (PMID 35327386, 2022). "Several lines of evidence suggest that galectin-3 is beneficial in experimental kidney diseases such as polycystic kidney disease, nephrotoxic nephritis and unilateral ureteric obstruction (UUO), but its functional importance in FA-induced acute kidney injury is unknown." (PMID 21494626, 2011).
heart disease (49 papers, 2012 to 2025). "For example, LGALS3, which encodes for galectin-3 has been suggested as an early-stage circulating biomarker for various diseases including heart disease." (PMID 38416769, 2024). "Among these biomarkers, galectin-3 (Gal-3) is notable for its involvement in inflammation and tissue fibrosis associated with cardiac disease." (PMID 39272333, 2024). "Of note, Lgals3 is currently developed as a new generation diagnostic marker for detecting the early stages of various heart diseases." (PMID 35203431, 2022). "Despite these limitations, the present study demonstrates the possibility of using circulating galectin-3 concentration as a clinically useful diagnostic biomarker in dogs with heart diseases." (PMID 34722704, 2021). "Galectin-3 plays a prominent role in chronic inflammation and has been implicated in the development of many disease conditions, including heart disease." (PMID 35053194, 2021). "Furthermore, we describe how galectin-3 may be useful as a diagnostic marker for detecting the early stages of various heart diseases, which may contribute to improved early therapeutic interventions." (PMID 32899694, 2020). "The potential biomarker for heart disease Galectin-3 (Gal-3), upregulating the expression and activity of KCa3.1 channel in inflammatory cells and fibroblasts." (PMID 36072583, 2022). "As the results concerning Galectin-3 concentrations from the current study and former studies are discordant, the usefulness of Galectin-3 in heart disease should be further investigated." (PMID 35780161, 2022). "They detected significantly higher concentrations of Galectin-3 in dogs with cardiac (1.12 ± 0.83 ng/mL) and non-cardiac diseases (2.27 ± 2.59 ng/mL) compared to the healthy group (0.64 ± 0.15 ng/mL)." (PMID 35780161, 2022). "The correlation between the galectin-3 levels and conventional echocardiographic indices was assessed in eight healthy dogs and 26 dogs with heart diseases." (PMID 34722704, 2021). "The serum galectin-3 levels were analyzed according to the heart disease type in the cardiac disease group." (PMID 34722704, 2021). "Among dogs with heart diseases, dogs with concentric cardiomyopathy had significantly increased circulatory galectin-3 levels compared with healthy dogs (p = 0.028)." (PMID 34722704, 2021). "Galectin-3 levels in the healthy, cardiac, and non-cardiac disease groups were 0.64 ± 0.15, 1.12 ± 0.83, and 2.27 ± 2.59 ng/ml, respectively." (PMID 34722704, 2021). "Dogs with non-cardiac diseases had significantly elevated galectin-3 levels compared with healthy dogs (p = 0.016)." (PMID 34722704, 2021). "The aim of this article is to concisely review the diagnostic and prognostic role of galectin-3 and ST2 in different cardiac diseases." (PMID 34439833, 2021). "The ROC analysis was used to assess the cutoff values for the galectin-3 levels for predicting diastolic dysfunction among eight healthy dogs and 26 dogs with heart diseases." (PMID 34722704, 2021). "The dogs with cardiac disease (1.12 ± 0.83 ng/ml) had significantly higher galectin-3 levels than the healthy dogs (0.64 ± 0.15 ng/ml, p = 0.009)." (PMID 34722704, 2021). "This study showed that dogs with heart diseases had significantly higher serum galectin-3 levels than healthy dogs." (PMID 34722704, 2021). "Further large-scale research is required to evaluate the role of circulating galectin-3 in dogs with heart diseases." (PMID 34722704, 2021). "In conclusion, this study has demonstrated that the circulating galectin-3 concentration increases in dogs with heart diseases as well as in dogs with endocrine and skin diseases." (PMID 34722704, 2021). "The major finding of this study was the elevation of serum galectin-3 concentration in dogs with heart diseases, endocrine diseases, and dermatologic diseases compared with healthy dogs." (PMID 34722704, 2021).
heart disease (continued). "The correlation between the galectin-3 and NT-proBNP levels was analyzed according to the heart disease type in the cardiac disease group." (PMID 34722704, 2021). "In this review, we discuss and summarize recent developments of galectin-3 as a next-generation molecular biomarker of heart disease." (PMID 32899694, 2020). "Because of its involvement in cardiac fibrosis, inflammation and remodelling processes, galectin-3 (Gal-3) is one of the emerging biomarkers in cardiac diseases." (PMID 25875595, 2015). "Galectin-3 has been identified as a potential biomarker that may be a predictor of prognosis and treatment in a variety of heart disease conditions." (PMID 39451549, 2024). "Galectin-3 is increased in different etiologies of heart disease." (PMID 37513890, 2023). "The finding that Galectin-3 was increased in dogs with concentric cardiac diseases could indicate that this biomarker might be more suitable for investigating other cardiac diseases than DMVD." (PMID 35780161, 2022). "This study showed that galectin-3 could be used as a useful cardiac biomarker in diagnosing heart diseases and evaluating cardiac function in dogs." (PMID 34722704, 2021). "Treatment options for dogs with heart diseases varied in this study, so it might adversely affect the results of circulating galectin-3 levels." (PMID 34722704, 2021). "However, a few studies on the relationship between the circulating galectin-3 levels and various heart diseases have been conducted in veterinary medicine." (PMID 34722704, 2021). "Dogs with heart diseases had significantly higher galectin-3 levels than healthy dogs (p = 0.009)." (PMID 34722704, 2021). "Third, all dogs with heart diseases were treated with various treatment options, which might underestimate the concentration of circulating galectin-3 concentration." (PMID 34722704, 2021). "Therefore, studies on the prognostic evaluation of galectin-3 are required for dogs with various heart diseases." (PMID 34722704, 2021). "Thus, the aim of this review is to provide an overview of a candidate molecular heart disease biomarker, galectin-3 (Gal-3)." (PMID 32899694, 2020). "This could indicate that Galectin-3 might be more responsive to non-cardiac diseases in dogs." (PMID 35780161, 2022). "In cardiac diseases, galectin-3 has been widely known as cardiac biomarkers reflecting cardiac fibrosis in both humans and dogs, and the results of this study supported the previous results that dogs affected by heart diseases had significantly higher galectin-3 levels than healthy dogs." (PMID 34722704, 2021). "Therefore, further large-scale studies on evaluating galectin-3 levels in dogs with LVH according to the underlying causes including heart disease or non-cardiac diseases will be needed." (PMID 34722704, 2021). "Moreover, galectin-3 levels might be a reliable predictor for cardiac remodeling in dogs with heart diseases." (PMID 34722704, 2021). "In addition to analyzing the effect of medications on galectin-3 concentration, further studies will be needed to find the association between survival times and the progression of diseases with galectin-3 levels in dogs with heart diseases on different treatments." (PMID 34722704, 2021). "Therefore, it is suggested that galectin-3 levels could be applied to predict for diastolic dysfunction in dogs with heart diseases." (PMID 34722704, 2021). "An effect of galectin-3 inhibitors on non-cirrhotic heart diseases is the attenuation of collagen deposition." (PMID 37513890, 2023). "This is because the level of circulating galectin-3 in patients with different stages of heart disease does not differentiate between myocarditis and fibrosis and therefore it does not specifically reflect these conditions." (PMID 35053194, 2021).
heart disease (continued). "The potential presence of myocardial structural remodeling in asymptomatic patients and, thus, early subclinical cardiac disease in T2DM patients, could partially explain the higher levels of galectin-3 found in the diabetic group." (PMID 32294902, 2020). "The present review aims to summarize the role of galectin-3 in non-cirrhotic cardiac diseases and cirrhotic cardiomyopathy and to explore whether it may be a therapeutic target in cirrhotic cardiomyopathy." (PMID 37513890, 2023). "Additionally, it is important to note that the Galectin-3 concentrations in dogs with non-cardiac diseases like endocrine or dermatologic diseases were even higher than in dogs with cardiac diseases." (PMID 35780161, 2022). "On the other hand, galectin-3 activates fibroblasts and enhances synthesis of the collagen I and III types that were proved earlier in several studies in animal models N-terminal propeptide of procollagen I and III types are deposited directly into the myocardium in various heart diseases." (PMID 32784491, 2020). "In middle-aged patients without overt heart disease, advanced echocardiographic parameters (particularly strain and EMD), combined with biomarkers such as galectin-3 and hsTnI, represent sensitive markers for early atrial dysfunction and AtCM." (PMID 40709024, 2025).
neurodegenerative disease (46 papers, 2016 to 2026). A disorder of the central nervous system characterized by gradual and progressive loss of neural tissue and neurologic function. "The role of Galectin-3 (Gal3), encoded by the Lgals3 gene, in neurodegenerative diseases has recently attracted much attention." (PMID 37988169, 2024). "Recent research studies have established a connection between galectin-3 and both peripheral information and neuroinflammation, with positive associations noted between galectin-3 and cardiovascular as well as neurodegenerative diseases." (PMID 38755574, 2024). "Loss of galectin-3 has been associated with reduced neuroinflammation in mouse models of brain degeneration." (PMID 36115971, 2022). "In models of other neurodegenerative diseases, galectin-3 has also been linked to damage and neuroinflammation." (PMID 36008956, 2022). "Although the underlying mechanism to define the function of galectin-3 in neurodegenerative disease is not fully understood, it may depend on the timing and context of disease status." (PMID 34720894, 2021). "A common feature across these activated states is the upregulation of galectin-3 (Gal3), a β-galactoside-binding lectin that has emerged as a critical regulator of microglial activation and function in neurodegenerative diseases." (PMID 41487996, 2025). "In recent years, biomarkers such as Galectin-3 and Cardiotrophin-1 have been studied in inflammatory and degenerative diseases." (PMID 40431592, 2025). "In recent years, biomarkers, such as Galectin-3 and Cardiotrophin-1, have been investigated in inflammatory and degenerative diseases." (PMID 40431592, 2025). "Galectin-3 (Gal3) is a pleiotropic lectin commonly produced by immune cells with high impact on neurodegenerative diseases." (PMID 41487996, 2025). "Recently, Lgals3/galectin-3 has been shown to regulate the balance between pro-inflammatory and anti-inflammatory effects of microglia in neurodegenerative diseases." (PMID 39595213, 2024). "There have been some reports that galectin-3 of the microglia is important in the CNS, and galectin-3 has recently been the focus of many researchers in the neurodegenerative disease field." (PMID 38596358, 2024). "Inhibition of microglial galectin-3 expression can effectively decrease inflammatory responses in cells, alleviate the symptoms of neurodegenerative diseases in animal models, and increase the lifespan of R6/2 mice." (PMID 35219323, 2022). "In the subgroup analysis by galectin type, a higher galectin-3 expression is observed in patients with neurodegenerative diseases." (PMID 36008956, 2022). "Upregulated genes in DAM, also known as Aβ-plaque-associated microglia, include Axl, Apoe, Clec7a, Itgax, Galectin 3 (LGALS3), and cystatin F (CST7), which are considered to be involved in neurodegenerative diseases." (PMID 36209099, 2022). "Galectin-3 has been defined as a mediator of microglial inflammatory responses in different preclinical models of brain degeneration." (PMID 36115971, 2022). "As can be seen, most studies point to an increase in the expression of galectins in neurodegenerative diseases, and most of these have focused on evaluating galectin-3 since it is the one for which the most function has been described in the nervous system." (PMID 36008956, 2022). "Some scholars have pointed out that Lgals3 plays an important role in regulating microglial activation and neuroinflammation, serving as a biomarker of neurodegenerative diseases." (PMID 36030234, 2022). "Several studies reported increased galectin-3 levels during the onset and progression of disease pathology in neurodegenerative diseases." (PMID 36115971, 2022). "Neuroinflammation is a common factor in neurodegenerative diseases, and it has been demonstrated that galectin-3 activates microglia and astrocytes, leading to inflammation." (PMID 33414713, 2020). "The investigations of the roles of Galectin-3 in neurodegenerative diseases are still in nascent phase." (PMID 32455781, 2020).